PCSK9 (proprotein convertase subtilisin/kexin type 9)
Diseases named in the same sentence as PCSK9 in open-access papers (continued):
Sharing a sentence is not in itself a finding about the gene and the disease.
Sepsis (77 papers, 2016 to 2026). Sepsis is defined as life-threatening organ dysfunction caused by a dysregulated host response to infection. "In our study, the causal role of the reduced susceptibility to sepsis by ω-3 fatty acids was connected to the SNP of PCSK9." (PMID 41608459, 2026). "Surprisingly, the presence of mutant alleles of PCSK9, including the rs11591147 mutation, reduced the risk of death from sepsis, although the underlying mechanism of this phenomenon remains to be elucidated." (PMID 41608459, 2026). "In sepsis, high plasma PCSK9 levels are associated with acute organ failure and increased mortality." (PMID 41608459, 2026). "In summary, this study revealed a positive association between SREBP-2 and PCSK9 plasma levels, as well as cholesteryl ester levels, in patients with sepsis." (PMID 41233786, 2025). "PCSK9 levels are elevated in sepsis, but their associations with disease severity and acute organ failure remain inconclusive." (PMID 39948564, 2025). "SARS-CoV-2 infection was associated with higher plasma PCSK9 levels compared to similarly ill patients with sepsis/septic shock." (PMID 41233786, 2025). "PCSK9 loss-of-function mutations were associated with better survival in sepsis, while high plasma PCSK9 levels or PCSK9 gain-of-function mutant carriers were described to contribute to disease severity and death." (PMID 39408818, 2024). "For instance, elevated serum PCSK9 levels in sepsis patients have been closely linked to the development of multiple organ failure." (PMID 39584843, 2024). "Patients with liver cirrhosis have a higher risk for infections and sepsis, and the plasma PCSK9 level of these patients has been described as low." (PMID 37515197, 2023). "This study demonstrated that PCSK9 levels at or above 370 ng/ml significantly increase the risk of 28-day mortality in sepsis, providing evidence to evaluate the potential clinical significance of circulating PCSK9 in assessing the prognosis of septic." (PMID 37904138, 2023). "Pro-protein convertase subtilisin/kexin 9 (PCSK9) decreases the clearance of the pathogenic lipids, supporting the potential role of PCSK9 in the prognosis of sepsis." (PMID 37904138, 2023). "Causal relationships between PCSK9 level and the severity of sepsis are supported by clinical, experimental, and genetic studies." (PMID 37904138, 2023). "Time-dependent receiver operating characteristic curves and Cox proportional hazards regression were used to evaluate the association between PCSK9 level and 28-day mortality of sepsis." (PMID 37904138, 2023). "Recent studies have described the ability of PCSK9 inhibitors, potent lipid-lowering agents, in decreasing the risk of sepsis." (PMID 37587410, 2023). "Recent experimental and clinical studies have also supported a central role of PCSK9 in the clearance of pathogenic lipids such as the bacterial lipopolysaccharide (LPS) and in sepsis." (PMID 36119052, 2022). "Sepsis in patients with PCSK9 gain-of-function mutations was related to reduced survival, which correlates with the 2–3-fold increased plasma PCSK9 levels in patients with sepsis and their more fatal illness." (PMID 35162992, 2022). "PCSK9 has recently been implicated as a critical mediator of the immune response to sepsis, whereby PCSK9 inhibits hepatic clearance of lipopolysaccharide in the liver leading to increased inflammation and worse outcomes." (PMID 35770004, 2022). "Human PCSK9 loss-of-function mutant carriers displayed reduced IL-6 blood levels shortly after LPS injection and were associated with increased survival after sepsis." (PMID 35162992, 2022). "Secondary genetic analyses of larger sepsis trials have shown a correlation between lower plasma PCSK9, and PCSK9 loss of function with decreased sepsis mortality." (PMID 33920038, 2021).
Sepsis (continued). "PCSK9 LOF mutations improve survival outcomes during sepsis, while PCSK9 GOF mutations increase mortality and thus are detrimental in septic shock patients." (PMID 34070931, 2021). "On this basis, PCSK9 is involved in the modulation of cholesterol and pathogenic lipid levels in sepsis." (PMID 33123601, 2020). "In clinical studies, PCSK9 plasma concentrations were markedly elevated in trauma as well as in sepsis patients, and significant associations with severity of illness and organ failure have been shown." (PMID 31843964, 2020). "Nowadays, studies on the roles of PCSK9 in the infection mediated by pathogenic bacteria are mainly focused on sepsis." (PMID 33123601, 2020). "In patients admitted to the hospital with serious infection, is there a significant association between PCSK9 genetic variation and risk of sepsis?" (PMID 31509211, 2019). "Among first-infection hospitalizations, we also sought to determine if PCSK9 LOF variants are associated with odds of sepsis." (PMID 30726226, 2019). "Elevated proprotein convertase subtilisin/kexin type 9 (PCSK9) levels have been associated with adverse outcomes in patients hospitalized for sepsis." (PMID 30726226, 2019). "The same PCSK9 LOF variants in human sepsis are associated with increased survival and decreased organ dysfunction." (PMID 31332258, 2019). "Association of PCSK9 loss-of-function variants and risk of serious infection and sepsis hospitalizations." (PMID 30726226, 2019). "Nevertheless, we cannot exclude the possibility that beneficial effects of PCSK9 variants on sepsis outcomes would be observed after patients are discharged from hospital." (PMID 31509211, 2019). "Less information is available to date about PCSK9 and its association with LPS clearance and sepsis in humans." (PMID 31509211, 2019). "Given the associations between PCSK9 and LDL-C, and then LDL-C and immune response, there are plausible connections between PCSK9 variants and risk of hospitalization for serious infections and sepsis." (PMID 30726226, 2019). "This cohort study tests the associations between PCSK9 genetic variants, a PCSK9 genetic risk score, or genetically estimated PCSK9 expression levels and the risk of sepsis among patients admitted to a hospital with infection." (PMID 31509211, 2019). "Patients who have PCSK9 loss-of-function variants also have decreased readmission rate for sepsis after an episode of sepsis suggesting long term benefits of impaired PCSK9 function." (PMID 30736368, 2019). "The presence of multiple PCSK9 loss-of-function alleles seems to decrease the risk of one-year death or infection-related readmission in sepsis survivors." (PMID 31635200, 2019). "PCSK9 inhibition results in decreased inflammatory cytokine production and physiological responses to endotoxin in septic mice and increased PCSK9 levels are associated with reduced endotoxin clearance and organ failure in sepsis." (PMID 28010729, 2016). "Among which rs11591147 in the PCSK9 gene (a loss-of-function variant) may mediate the protective effect of PUFAs against sepsis." (PMID 41608459, 2026). "Nevertheless, it remains uncertain whether the benefits of PCSK9 inhibition are associated with circulating PUFAs levels in patients with sepsis." (PMID 41608459, 2026). "It is possible that the protective effect of ω-3 PUFAs in sepsis is mediated by mutations in PCSK9." (PMID 41608459, 2026). "Moreover, the PCSK9 rs11591147 variant emerges as a mediator, offering a novel genetic biomarker of sepsis susceptibility." (PMID 41608459, 2026). "Mendelian randomization analysis and experimental validation indicated that in patients with PCSK9 gene mutations, high levels of circulating polyunsaturated fatty acids (PUFAs), particularly ω-3 PUFAs, may reduce susceptibility to sepsis." (PMID 41608459, 2026). "Levels of PCSK9 in the blood of patients with sepsis are increased, but its association with disease severity remains unclear." (PMID 41233786, 2025).
Sepsis (continued). "Notably, the administration of the PCSK9 inhibitor evolocumab effectively alleviated the pathological changes caused by sepsis and inhibited the onset and progression of pulmonary microthrombosis." (PMID 41462858, 2025). "Moreover, PCSK-9 knockout is associated with reduced bacterial dissemination, organ dysfunction and inflammation in a murine model of sepsis." (PMID 38521954, 2024). "PCSK9 gain-of-function mutation carriers had reduced survival in sepsis." (PMID 39051245, 2024). "Patients with PCSK9 loss-of-function mutations displayed lower interleukin (IL)-6 levels in the blood after lipopolysaccharide injection and had increased survival after sepsis." (PMID 39051245, 2024). "Two previous cohort studies supported the association between PCSK9 and sepsis outcomes." (PMID 38972879, 2024). "Interestingly, PCSK9 has been confirmed to be a sensitive and independent predictive risk factor for the prognosis of patients in the early stages of sepsis." (PMID 39736777, 2024). "Therefore, it is recommendable to calculate associations of PCSK9 with disease severity and/or mortality in sepsis patients following the exclusion of patients with severe chronic liver diseases." (PMID 37515197, 2023). "Clinical studies have reported that patients with sepsis had increased sera levels of PCSK9, indicating PCSK9 as a biomarker of septic disorder, while other studies showed that PCSK9 content is positively associated with liver and kidney damage in septic mouse models." (PMID 37587410, 2023). "We report on the independent association between PCSK9 loss-of-function genotype and markers of endothelial dysfunction in a large cohort of critically ill children with septic shock with corroborative evidence in juvenile murine sepsis." (PMID 36778250, 2023). "Thus, a conceptual model exists whereby PCSK9 is an inhibitor of clearance of circulating LPS in sepsis, and reduced PCSK9 activity is associated with an attenuated inflammatory response and improved outcome." (PMID 35770004, 2022). "Conversely, PCSK9 deficiency reduces circulating levels of cell-free DNA (cfDNA), a strong prognostic biomarker in sepsis and considered as an important link among innate immunity, inflammation and coagulation, with both procoagulant and antifibrinolytic properties." (PMID 34070931, 2021). "As PCSK9 regulates the hepatic expression of LDL-Rs, and LDL-Rs contribute to the clearance of lipopolysaccharides (LPS) from circulation, PCSK9 deficiency was expected to improve the outcome in animal sepsis models including sepsis-dependent renal dysfunction." (PMID 33364976, 2020). "Thus, deficiency of PCSK9 seems to be beneficial in infection and sepsis due to improved endotoxin clearance." (PMID 31843964, 2020). "Finally, the in vivo results were supported by the results of the clinical studies, in which patients with sepsis carrying a PCSK9 LOF (loss of function) allele had decreased plasma levels of proinflammatory cytokines such as TNF-α, IL-6, and IL-8." (PMID 32456228, 2020). "However, we cannot exclude a potential effect of PCSK9 on outcomes in patients with sepsis associated with specific causes, or those with specific manifestations of sepsis." (PMID 31509211, 2019). "There is a significant amount of convincing data indicating that serious infections and sepsis might be associated with elevated plasma PCSK9 levels." (PMID 31635200, 2019). "Our recent studies also demonstrate that PCSK9 overexpression exacerbates sepsis pathophysiology through increased inflammation in the lungs and liver, whereas PCSK9 deficiency reduces the infectious burden, lung inflammation, and hepatocellular injury in septic mice." (PMID 30002483, 2018). "We used PCSK9 loss-of-function genotype as a surrogate to mark PCSK9 inhibition in vivo; however, it is unclear whether our PCSK9 genotype findings will translate to effects on sepsis outcomes by modulating PCSK9 with PCSK9-inhibiting drugs." (PMID 29510719, 2018).
Sepsis (continued). "In contrast, increased clearance of LDL during sepsis (for example, by loss-of-function genotypes of PCSK9) may be beneficial because pathogen lipids within LDL particles are cleared along with LDL more rapidly." (PMID 29510719, 2018). "Therefore, early detection of PUFA levels and PCSK9 genotypes, along with the targeted nutritional supplements, may help reduce sepsis risk in susceptible populations." (PMID 41608459, 2026). "Therefore, we hypothesized that PCSK9 loss-of-function would enhance the protective effect of ω-3 PUFAs supplementation against sepsis." (PMID 41608459, 2026). "In patients with PCSK9 mutations, elevated plasma ω-3 PUFAs may reduce susceptibility to sepsis." (PMID 41608459, 2026). "Whether the PCSK9 gene is associated with the progress from infection to sepsis is unknown to date." (PMID 31509211, 2019). "Thus, in patients with low versus high VAT/SAT ratios, we examined the effect of statins to understand the effect of decreased LDL production, and examined the effect of PCSK9 loss-of-function genotype to understand the effect of increased LDL clearance in patients with sepsis." (PMID 29510719, 2018). "Variants of PCSK9 were associated with outcomes of sepsis, and post treatment of cecal ligation and perforation model mice with PCSK9 inhibitors decreased inflammation, cardiovascular dysfunction, and mortality; thus, PCSK9 inhibition could be effective in sepsis." (PMID 27384443, 2016). "In sepsis, PCSK9 degrades low-density lipoprotein (LDL) receptors in hepatocytes and very low-density lipoprotein (VLDL) receptors in adipocytes, thereby diminishing pathogenic lipid uptake and clearance." (PMID 41608459, 2026). "Identifying PCSK9 rs11591147 as a mediator links genetic epidemiology to molecular biology and suggests a therapeutic target for sepsis prevention and treatment." (PMID 41608459, 2026). "Our data show that the expression of PCSK9 in septic mice is significantly elevated, which is consistent with the previously reported elevated levels of circulating PCSK9 in patients with sepsis or systemic inflammation." (PMID 41462858, 2025). "Increased PCSK9 levels in sepsis are thought to contribute to the severity of the disease through mechanisms that have yet to be fully elucidated." (PMID 40265438, 2025). "On the contrary, evolocumab significantly normalized these parameters, indicating that inhibiting PCSK9 can alleviate platelet hyperactivity in patients with sepsis." (PMID 41462858, 2025). "PCSK9 exacerbated platelet activation and NETs levels in sepsis mice, while PCSK9 inhibitor evolocumab reduced these levels." (PMID 41462858, 2025). "The pharmacological inhibition of PCSK9 by evolocumab effectively reversed these effects, providing a promising therapeutic strategy for alleviating thrombotic complications in sepsis-induced lung injury." (PMID 41462858, 2025). "Proprotein convertase subtilisin/kexin type 9 (PCSK9) is another protein that is induced in patients with sepsis." (PMID 39948564, 2025). "Previously, our group reported higher levels of PCSK9 in the plasma of SARS-CoV-2 infected sepsis patients compared to patients with different disease etiologies." (PMID 41233786, 2025). "PCSK9 can exacerbate the hypercoagulable state in sepsis, as evidenced by a decreased R value, shortened K time, increased Angle, and elevated MA." (PMID 41462858, 2025). "Clinical studies have suggested that PCSK9 plays a crucial role in the pathogenesis of sepsis, and that inhibition of its activity can effectively improve the prognosis of affected patients." (PMID 41462858, 2025). "This study provides new insights into the role of PCSK9 in regulating platelet activation and NET formation and offers novel findings regarding the involvement of PCSK9 in sepsis-induced pulmonary microthrombosis." (PMID 41462858, 2025). "By establishing a complete mouse model of CLP, we found that the expression of PCSK9 and platelet activation were significantly increased during sepsis." (PMID 41462858, 2025).
Sepsis (continued). "This study investigated plasma sLOX-1 levels in patients with SIRS, sepsis, or septic shock, examining associations with CRP and PCSK9 levels, disease severity, SARS-CoV-2 infection, and underlying liver cirrhosis." (PMID 39948564, 2025). "Compared to the mice in the control + vehicle group, the expression of PCSK9 in the lung tissue of mice in the sepsis + vehicle group showed a modest increase." (PMID 41462858, 2025). "In this study, we provided compelling evidence that PCSK9 exacerbated pulmonary microthrombosis in patients with sepsis by promoting platelet activation and subsequent formation of NETs." (PMID 41462858, 2025). "In this study, the sepsis group had significantly higher PCSK9 levels than the control group, which is in agreement with the results of Boyd and his coworkers in 201619." (PMID 38972879, 2024). "SARS-CoV-2 infection was shown to induce proprotein convertase subtilisin/kexin type 9 (PCSK9) plasma levels in sepsis." (PMID 39051245, 2024). "We found that LDL-C and PCSK9 were significantly higher in each of the two sepsis groups than the control group, as p ≤ 0.001 in all, except for PCSK9 in the sepsis group when compared to the control group, as p = 0.01." (PMID 38972879, 2024). "In conclusion, the PCSK9 assay can be used as a biomarker for bad prognosis in children suffering from clinical sepsis." (PMID 38972879, 2024). "A recent meta-analysis of 20 double-blind, randomized, placebo-controlled trials, encompassing 64,984 participants, was conducted to determine the impact of PCSK9-iTs on the occurrence of sepsis and other severe infections." (PMID 38185721, 2024). "In a mouse sepsis model, PCSK9 overexpression exacerbated lung and liver inflammation, whereas PCSK9 deficiency reduced levels of IL-6 in the blood and reduced organ inflammation." (PMID 38445291, 2024). "Proprotein convertase subtilisin/kexin type 9 (PCSK9) is an enzyme released in response to the drop in cholesterol level occurring in sepsis." (PMID 38972879, 2024). "Our study aimed to evaluate the prognostic role of serum Proprotein convertase subtilisin/kexin type 9 (PCSK9) level in children with sepsis and severe sepsis." (PMID 38972879, 2024). "PCSK-9 levels are elevated in patients with sepsis and expression is upregulated in various models of sepsis." (PMID 38521954, 2024). "We sought to determine the safety of administering a subcutaneous PCSK9 inhibitor (alirocumab) at a single dose of 300 mg in patients with severe sepsis or septic shock." (PMID 39584843, 2024). "Their data confirmed that inhibition of PCSK9 prevented TLR4 activation during sepsis, improved vascular function and increased survival in septic mice." (PMID 39736777, 2024). "This can be attributed to the fact that in the early hours of sepsis, there is a significant decline in plasma cholesterol levels, which stimulates hepatocytes to increase PCSK9 production." (PMID 38972879, 2024). "Clinical research has highlighted PCSK9 as a critical player in the pathogenesis of sepsis, with findings indicating that inhibiting PCSK9 activity can substantially enhance sepsis outcomes." (PMID 39584843, 2024). "The severe sepsis group in this study had significantly higher PCSK9 and LDL-C levels than the sepsis group, as an increase in PCSK9 levels was reported with the development of organ failure in sepsis." (PMID 38972879, 2024). "In accordance with the current findings, several studies have reported that PCSK9 levels are increased in sepsis." (PMID 37515197, 2023).